DEFA3 (defensin alpha 3)
Diseases named in the same sentence as DEFA3 in open-access papers (continued):
Sharing a sentence is not in itself a finding about the gene and the disease.
influenza (1 paper, 2024). An acute viral infection of the respiratory tract, occurring in isolated cases, in epidemics, or in pandemics; it is caused by serologically different strains of viruses (influenzaviruses) designated A, B, and C, has a 3-day incubation period, and usually lasts for 3 to 10 days. "LASSO analysis showed that severe influenza was significantly correlated with duration of illness, age, bacterial status, DEFA3, HP, and MPO." (PMID 39340342, 2024).
malaria (1 paper, 2022). Malaria is a serious and sometimes fatal disease caused by a parasite that commonly infects a certain type of mosquito which feeds on humans. "It has been reported that the neutrophil granule proteins MMP8, OLFM4, DEFA3, and ELANE are increased in severe malaria versus uncomplicated malaria." (PMID 36380373, 2022).
malignant tumors of the salivary glands (1 paper, 2024). "On its part, DEFA3 is overexpressed in both benign and malignant tumors of the salivary glands." (PMID 39201614, 2024).
mucinous adenocarcinoma (1 paper, 2022). An invasive adenocarcinoma composed of malignant glandular cells which contain intracytoplasmic mucin. "Compared with normal tissues, the fold change of DEFA3 in colonic mucinous adenocarcinoma was 1.986 (TCGA Colorectal Statistics)." (PMID 36703795, 2022).
periodontitis (1 paper, 2023). An acute or chronic inflammatory process that affects the tissues that surround and support the teeth. "It is connected with antimicrobial activity because, in the pathogenesis of periodontitis, antimicrobial proteins such as DEFA3 can cooperate with other inflammatory proteins and regulate distinct inflammatory pathways." (PMID 36949424, 2023).
pneumonia (1 paper, 2013). An acute, acute and chronic, or chronic inflammation focally or diffusely affecting the lung parenchyma, caused by an infection in one or both of the lungs (by bacteria, viruses, fungi, or mycoplasma.). "The top 50 over-abundant transcripts in pneumonia were dominated by antimicrobial neutrophil-related genes e.g ELANE, DEFA1B, MMP8, CAMP, DEFA3, DEFA4, MPO, LTF." (PMID 23940611, 2013).
tuberculosis (1 paper, 2025). A chronic, recurrent infection caused by the bacterium Mycobacterium tuberculosis. "DEFA3 represents a promising biomarker in the fight against tuberculosis, offering insights into disease mechanisms and potential new avenues for diagnosis and treatment." (PMID 40491837, 2025).
urinary tract infection (1 paper, 2018). "Reduced DEFA1/DEFA3 copy number has been associated with higher susceptibility to recurrent urinary tract infections (UTIs) in children with vesicoureteral reflux and HIV infection." (PMID 29950924, 2018).
viral infection (1 paper, 2025). "One such compensatory mechanism is the heightened activation of DEFA3, which plays a critical role in immune defense or the pro-inflammatory response (mediated by NF-kappaB), which may exacerbate inflammation rather than effectively control viral infection." (PMID 39859341, 2025).
viral pneumonia (1 paper, 2018). Inflammation of the lung parenchyma that is caused by a viral infection. "Among the 87 defensins and associated genes that had expression values available, DEFA4 and DEFA3 were the most significantly differentially expressing defensins between bacterial and viral pneumonia patients." (PMID 30524393, 2018).
tumor (13 papers, 2010 to 2025). "For example, genetic manipulation of DEFA3, MMP11, or MYL9 in APC Min/+ mice would directly reveal their causal roles in tumor initiation, progression, or metastasis." (PMID 41009818, 2025). "Other key transcripts, such as MPO and DEFA3, further emphasize the role of neutrophil extracellular traps and their immune activity in tumor progression." (PMID 40003985, 2025). "Although our findings suggest that DEFA3 acts as a tumor suppressor in CT26 cells and is downregulated in murine tumors, previous reports have described conflicting roles for other DEFA family members." (PMID 41009818, 2025). "DEFA1, DEFA2, and DEFA3 are expressed in renal cell carcinoma cells and may directly affect tumor proliferation." (PMID 36703795, 2022). "This could suggest similar effects exerted by DEFA3 on tumor cells." (PMID 39201614, 2024). "DEFA3 was upregulated in tumor tissue compared with the normal colonic mucosa and negatively correlated with the prognosis in patients with CRC." (PMID 34336846, 2021). "These HLA-A24 ligands were possibly overexpressed in tumor samples and were therefore chosen as nonmutated TAA candidates of CRC111, which comprised peptides encoded by the KLK8, DEFA3, STRIP2, MMP1, FSCN1, TBX15, and PHLDA1 genes." (PMID 34185709, 2021). "Three genes, DEFA1, DEFA3 and LOC728358, map to a refined region in 8p23.1 (8:6789275-6889920) and the ANGPT2 gene maps an adjacent region (8:6342789-6444367) and all show decreases expression in the tumor samples." (PMID 20799942, 2010). "Although we demonstrated that DEFA3 inhibits proliferation and migration of CT26 cells in vitro, and linked MMP11/MYL9 expression to advanced CRC in human datasets, we did not test the functional impact of these genes in living tumor models." (PMID 41009818, 2025).
infection (8 papers, 2006 to 2025). The state of being infected such as from the introduction of a foreign agent such as serum, vaccine, antigenic substance or organism. "This could be the case of DEFA1A3 in which variation in DEFA1 and DEFA3 copy number, and DEFA3 absence could underlie variable resistance to infection among individuals." (PMID 17214878, 2007). "Elevated levels of DEFA3 indicate a strengthened antimicrobial defense, potentially as a response to increased infection or stress in DKD patients." (PMID 41498039, 2025). "In addition, DEFA1/DEFA3 CNV has been associated with inflammation, infection, and several autoimmune diseases." (PMID 29950924, 2018). "DEFA1/DEFA3, genes encoding human neutrophil peptides (HNP) 1–3, display wide-ranging copy number variations (CNVs) and is functionally associated with innate immunity and infections." (PMID 29950924, 2018). "Lower DEFA1/DEFA3 CNV may lead to impaired innate defenses and subdued inflammatory signals, which may ultimately be permissive to infections." (PMID 29950924, 2018). "In addition, the polymorphisms were not important predictors of susceptibility to infection, suggesting that they do not influence DEFA1/DEFA3-mediated or DEFB1-mediated responses to infection." (PMID 16700921, 2006).
cancer (3 papers, 2021 to 2025). A tumor composed of atypical neoplastic, often pleomorphic cells that invade other tissues. "The defensin family genes (DEFA1, DEFA1B, DEFA3) and CD177, typically linked to neutrophil function, may indicate the involvement of innate immunity in cancer development." (PMID 40227838, 2025).
bacterial infection (1 paper, 2025). "Amongst the proteins identified during proteomic analysis that were decreased in CepEVs were DEFA3, LYZ, CAMP, LTF, and BPIFB1, all of which had strong associations with defense response to bacterium (GO: 0042742), as well as the immune response to bacterial infection." (PMID 41550953, 2025).
DEFA3 also shares sentences with these, for which no sentence is quoted: metastatic tumor (2 papers); appendicitis (1); atrioventricular block (1); coronary heart disease (1); dental caries (1); dyslipidemia (1); endothelial dysfunction (1); Hospital-Acquired Infections (1); idiopathic thrombocytopenic purpura (1); metastatic cancers (1); metastatic melanoma (1); Obesity (1); parasite infection (1); periodontal disease (1); prostate carcinoma (1); pulmonary TB (1); renal cell carcinoma (1); rheumatoid arthritis (1); schizophrenia (1); sialolithiasis (1); vesicoureteral reflux (1).